RNA5S15 (RNA, 5S ribosomal 15)
Synonyms: RN5S15
Gene: Ribosomal RNA gene on chromosome 1 (228,641,568 to 228,641,686, reverse strand). Ensembl gene ENSG00000201925.
Gene Ontology:
Molecular function: structural constituent of ribosome
Cellular component: ribosome
Homologues: Orthologues: dog 5S_rRNA (100% identical), rabbit 5S_rRNA (100% identical), chimpanzee 5S_rRNA (87% identical). Paralogues in human: RNA5S1 (100% identical), RNA5S10 (100% identical), RNA5S11 (100% identical), RNA5S12 (100% identical), RNA5S13 (100% identical), RNA5S14 (100% identical), RNA5S16 (100% identical), RNA5S17 (100% identical), RNA5S2 (100% identical), RNA5S3 (100% identical), RNA5S4 (100% identical), RNA5S5 (100% identical), and 26 more.